CDK4 (cyclin dependent kinase 4)
Diseases named in the same sentence as CDK4 in open-access papers (continued):
Sharing a sentence is not in itself a finding about the gene and the disease.
liver cancer (continued). "Given the importance of CDK4 in liver cancer, CDK4 inhibitors are utilized in HCC treatment." (PMID 32018226, 2020). "Among them, we hypothesized CDK4, an oncogene in liver cancer, might be a putative target gene of miR-338-3p in liver fibrosis." (PMID 28095789, 2017). "While downregulation of miR-145 and simultaneous upregulation of CDK4 has been shown for NSCLC, we found that also downregulation of miR-195 might play a similar role in CDK4 translational regulation, as is already known for bladder and liver cancer." (PMID 27588394, 2016). "However, whether the up-regulation of CDK4 in liver cancer is related to the invasion and metastasis of cancer cells remains elusive and needs further investigation." (PMID 34784846, 2021). "Interestingly, we found that CDK4 was highly expressed in liver cancer database." (PMID 34784846, 2021). "Interestingly, previous in vitro investigation reported a cell cycle arrest in the G1 phase in liver cancer cells treated with ponatinib, and identified that this cell cycle blockade was mediated by a reduction in the function of the CDK4/CDK6/Cyclin D1 complex." (PMID 32719607, 2020). "The therapeutic approach with targeting liver proliferation is also supported by several reports showing that cell cycle proteins CDK4, Cyclin D3, E2F1, and liver cancer promoting protein Gankyrin play a critical role in development of NAFLD." (PMID 37967813, 2024). "Possible therapies for the overexpressed kinases include CDK4/CDK6 inhibitors, such as Palbociclib, which has been shown effective in human liver cancer cell lines and mouse models with intact tumor suppressor Retinoblastoma (Rb1)." (PMID 35433463, 2022). "We analyzed the expressions of CDK4/6 and PI3K/AKT/mTOR in normal human tissues and liver cancer patient tissues through ualcan." (PMID 34335258, 2021). "Another study reported that RPA1 was increased in both liver cancer cell lines and HCC tissues and promoted the proliferation of HCC via the cyclin-dependent-kinase 4(CDK4)/cyclin-D pathway." (PMID 32552682, 2020). "H2A.Z.1 depletion selectively suppressed positive G1/S cell cycle components, such as CDK4, CDK6, cyclinD1 and CDK2, and simultaneously induced the expression of potent negative cell cycle regulators, p21WAF1/Cip1 and p27Kip1, in liver cancer cells." (PMID 26863632, 2016). "Our results indicate HOTAIR causes microsatellite instability (MSI) and abnormral expression of cell cycle related gene, e.g. CDK2, CyclinE, CDK4, CyclinD1, PCNA, ppRB, E2F1 in liver cancer stem cells." (PMID 26172293, 2015). "Taken together, these results suggest that galangin may induce apoptosis in liver cancer cells by disrupting the cell cycle through its influence on cell cycle proteins such as CCNB1, CDK4, CDK1, and PLK1." (PMID 38816744, 2024). "Through the construction of a protein interaction network and screening and verification of core targets, it was found that CDK1, SRC, CDK4 and E2F1 mRNA and protein expression levels were overexpressed in liver cancer tissues compared with normal liver tissues." (PMID 36699068, 2022). "The upregulation of CDK4 triggers the development of non-alcoholic fatty liver disease (NFALD), which leads to the phosphorylation of C/EBPα on Ser193 and the formation of C/EBPα-p300 complexes, resulting in hepatic steatosis, fibrosis, and liver cancer." (PMID 34055888, 2021). "In liver cancer, hsa_circ_0074817| EBF1 targets miR-539-5p, targeting CDK4 and SPAG5." (PMID 34055888, 2021). "In addition, based on website analysis, it predicted that the closely related gene of CDK4 was SFRS9, which was also highly expressed in liver cancer, and its expression was closely related to the stage of cancer." (PMID 34784846, 2021).
liver cancer (continued). "Our results showed that p21WAF1/CIP1 inhibited [3H]thymidine incorporation and reduced cdk2 kinase activity in human liver cancer cells but did not affect expression of cdk2 and cdk4." (PMID 11870547, 2002). "Therefore, these outcomes suggest that SFRS9 may also be a cancer-promoting factor in liver cancer,of course,whether it has a close relationship between SFRS9 with CDK4 and its related functions are worthy of further investigation." (PMID 34784846, 2021). "In addition, from the PPI sub-network of the genes adjacent to the aberrant DNA methylation sites, we found that among the key genes with a gene node degree greater or equal to 10, MYC, EIF4E, CDK4 and TGFB1 could stimulate the pathogenesis of liver cancer." (PMID 26046465, 2015). "Given this substantial number of downregulated tumor suppressors and elevation of cdk1 and cdk4, we conclude that fusion-positive HBLs/HCN-NOSs have more severe liver cancers relative to fusion-negative HBLs." (PMID 39796711, 2024).
endometrial cancer (28 papers, 2000 to 2025). Primary or metastatic malignant neoplasm involving the endometrium (mucous membrane that lines the endometrial cavity). "A similar association regarding CDK4/6 specific activity was reported in high-risk endometrial cancer." (PMID 32373071, 2020). "In our study, treatment with Palbociclib, a CDK4/6 inhibitor, significantly suppressed both cell proliferation and tumorsphere formation in endometrial cancer (EC) cells." (PMID 41287970, 2025). "To systematically identify the critical genes associated with CDK4/6 inhibitor sensitivity in EC, we performed a genome-wide CRISPR/Cas9 knockout screen in endometrial cancer." (PMID 41560755, 2025). "While genomic data suggest an oncogenic role for CDK4/6 in EC, a Phase-II trial combining letrozole and abemaciclib in estrogen receptor–positive recurrent endometrial cancer reported a superior combination treatment efficacy." (PMID 41560755, 2025). "Although CDK4/6 inhibition was considered, it was deferred in the setting of the patient’s age, advanced-stage endometrial cancer, and concern about potential drug tolerance in combination with chemotherapy and immunotherapy." (PMID 39076998, 2024). "In this study, it was confirmed that the expression of CyclinD1 and Cdk4 was decreased due to SNHG4 knock-down in endometrial cancer cells, and the arrest of the G1 phase was confirmed." (PMID 37189636, 2023). "A second, further downstream target that has been studied extensively in breast cancer and is now being evaluated in endometrial cancer are the cyclin-dependent kinases 4 and 6 (CDK4/6)." (PMID 36980685, 2023). "Western blot confirmed that knock-down of SNHG4 in two endometrial cancer cell lines regulates G1 arrest by CyclinD1, CDK4, and p27." (PMID 37189636, 2023). "The inhibition of CDK4/6 has gained attention recently with the published results of two clinical trials in the treatment of endometrial cancer." (PMID 36980685, 2023). "Abemaciclib, a selective CDK4 inhibitor, significantly inhibited endometrial carcinoma cell growth in the nude mice model." (PMID 36756714, 2023). "Consistent with previous studies, we found that depletion of PHF6 significantly decreased CDK4 expression and inhibited endometrial carcinoma cell proliferation in vitro and in vivo." (PMID 36756714, 2023). "Disruption of NF-κB signaling in endometrial cancer cells has been shown to induce G1 cell cycle arrest through the transcriptional down-regulation of Cyclin-dependent kinase 4 (CDK4) expression." (PMID 35328833, 2022). "ART inhibits endometrial cancer cell proliferation by disrupting the interaction between NF-κB and the CDK4 promoter and transcriptionally downregulates CDK4 expression." (PMID 35950034, 2022). "Our study showed similar results, where hinokitiol treatment for 48 h significantly reduced the expression of cyclin D1 and CDK4 in endometrial cancer cells." (PMID 34361036, 2021). "By inhibiting the CDK4/6 kinase, palbociclib disrupts this interaction and promotes ERα expression, ultimately sensitizing hormone-refractory endometrial cancer cells to endocrine therapy." (PMID 31330844, 2019). "Currently, the treatment options for advanced endometrial cancer patients are limited, and there is scant data with regards to the efficacy of palbociclib, a CDK4/6 specific inhibitor, towards endometrial cancer." (PMID 29969496, 2018). "Therefore, for patients with pMMR/MSS endometrial cancer, immunosuppressive agents in combination with targeted therapies (e.g., CDK4/6 inhibitors, anti-angiogenic agents) need to be explored to improve efficacy further." (PMID 40416974, 2025). "The first study published in endometrial cancer with the combination of letrozole and ribociclib, a third generation CDK4/6 inhibitor, showed that out of 20 ER+ endometrial cancer patients, 55% of patients were still on treatment at 12 weeks and 35% at 24 weeks." (PMID 36980685, 2023).
endometrial cancer (continued). "Based on what has been discovered regarding the molecular and genetic makeup of endometrial cancers, targeted therapies beyond mTOR and CDK4/6 have the possibility to increase activity when combined with hormonal therapy (e.g., MEK inhibitors and tyrosine kinase inhibitors)." (PMID 36980685, 2023). "Depletion of PHF6 might delay the growth of endometrial carcinoma cells through decreasing CDK4 expression." (PMID 36756714, 2023). "In this context, we reasoned that palbociclib, a CDK4/6 inhibitor that is capable of regulating the cell cycle machinery, could modulate ERα expression in endometrial cancer cells by affecting the NPM/B23 phosphorylation status." (PMID 31330844, 2019). "In addition, a phase II, open-label study of letrozole and ribociclib (CDK4/6 inhibitor) in patients with relapsed ER-positive ovarian cancer and endometrial cancer is underway (NCT02657928)." (PMID 28666422, 2017). "E2 activates the PKCδ/ERK pathway and enhances cyclin D1/cdk4 expression via the membrane-initiated signaling pathways mediated by ER-α36, suggesting a possible involvement of ER-α36 in E2-dependent growth-promoting effects in endometrial cancer cells." (PMID 21079811, 2010). "In conclusion, the expression of p16 and CDK4 may be an early event in the neoplastic transformation of endometrial cancer." (PMID 10682682, 2000). "High expression of CDK4 could promote the proliferation of endometrial carcinoma cells in vivo." (PMID 36756714, 2023). "Endometrial cancer (EC) harbors highly recurrent cell cycle pathway alterations, especially hyperactivation of the CCND1/CDK4/6 axis, raising the potential for use of CDK4/6 inhibitors in these cancers." (PMID 41560755, 2025). "In current study, we found that PHF6 affected the CDK4 and IL32 expression through transcriptional regulation in endometrial carcinoma cells." (PMID 36756714, 2023). "Among them, NCT03643510, in which cancer response is evaluated in a prospective, single arm phase II study of the combination of CDK4 and CDK6 dual inhibitor abemaciclib and selective estrogen receptor degrader fulvestrant in hormone receptor positive recurrent endometrial carcinomas." (PMID 35629078, 2022). "Overexpression of lncRNA ABHD11‐AS1 promoted the proliferation, G1‐S progression, invasion and migration of endometrial cancer cells; inhibited apoptosis; up‐regulated cyclin D1, CDK1, CDK2, CDK4, Bcl‐xl and VEGFA; and down‐regulated p16, while ABHD11‐AS1 down‐regulation has the opposite effect." (PMID 29799152, 2018). "We analysed p16 gene alteration and p16, cyclin-dependent kinase 4 (CDK4), CDK6, cyclin D1, cyclin D2, cyclin D3 and retinoblastoma protein (pRb) expression in ten normal endometriums (PE), 18 endometrial hyperplasias (EH) and 35 endometrial cancers (EC)." (PMID 10682682, 2000).
Ewing sarcoma (28 papers, 2014 to 2026). A small round cell tumor that lacks morphologic, immunohistochemical, and electron microscopic evidence of neuroectodermal differentiation. "Importantly, from a clinical perspective, mutations in RB are the strongest known predictor of resistance to CDK4/6 inhibitors, and Ewing sarcomas rarely contain RB mutations." (PMID 26337082, 2015). "We show how recurrent chromosome 8 gains drive poor patient outcomes via 4E-BP1 sensitizing for CDK4/6-inhibition in the Ewing sarcoma model." (PMID 41100815, 2025). "Translational data highlight the potential synergistic effect of dual targeting of IGFR and CDK4/6 in Ewing sarcoma." (PMID 40909947, 2025). "Despite the need for further preclinical and clinical investigations on the different oncological entities, this study recognized the relevance of CDK4/6 inhibition in Ewing sarcoma and, to a lesser extent, in rhabdomyosarcoma and other pediatric solid tumors." (PMID 41514647, 2025). "Tumors with low levels of CDK6 compared to CDK4 are universally sensitive to CDK4/6 inhibitors, including HR+ breast, mantle cell lymphomas, Ewing sarcomas as well as subsets of large tumor types, e.g. NSCLC." (PMID 36051751, 2022). "A combinatorial approach with anti-IGF1R mAb ganitumab and the CDK4/6 inhibitor palbociclib is currently under investigation in Ewing sarcoma (NCT04129151)." (PMID 34440844, 2021). "It is being tested to combine ganitumab with Src inhibitor dasatinib in patients with embryonal and alveolar rhabdomyosarcoma, and with chemotherapy, radiotherapy or CDK4/6 inhibitor in Ewing sarcoma." (PMID 32493414, 2020). "Using this approach, they identified the regulatory subunit of the protein phosphatase PP2A complex, STRN4, and the cyclin dependent kinase CDK4 as essential for Ewing sarcoma cell growth/survival." (PMID 26802024, 2016). "We report here significant efficacy of CDK4/6 and IGF-1R inhibitors on a rare Ewing's sarcoma with FUS-ERG fusion and CDKN2A/B loss in a PDOX model." (PMID 27286459, 2016). "Taken together, our data reveal sensitivity of Ewing sarcoma cells to CDK4/6 inhibition and support the further study of selective CDK4/6 inhibitors in this disease." (PMID 26337082, 2015). "We demonstrated that Ewing sarcoma cells require CDK4 and cyclin D1 for survival and anchorage-independent growth." (PMID 26337082, 2015). "Our combination of super-enhancer, functional genomic, and small-molecule screening has converged on the discovery of a dependency on cyclin D1 and CDK4 in Ewing sarcoma." (PMID 26337082, 2015). "We next validated the results of our functional genomic screening by analyzing the cyclin D1/CDK4 dependency in Ewing sarcoma in vitro." (PMID 26337082, 2015). "We found that CCND1 and CDK4 were expressed at higher levels in Ewing sarcoma cells compared to other G1 checkpoint transcripts based on RNA sequencing data from primary patient Ewing sarcoma tumors and cell lines." (PMID 26337082, 2015). "Amongst this compendium of cell lines, the expression of CCND1 is highest and the expression of CDK4 is the second highest in the ten Ewing sarcoma cell lines." (PMID 26337082, 2015). "In vivo, a CDK4/6 inhibitor decreased tumor growth and prolonged survival in a Ewing sarcoma xenograft model." (PMID 26337082, 2015). "We demonstrate that inhibition of CDK4 leads to cytostasis in a panel of Ewing sarcoma cell lines and cell death in a subset of these." (PMID 26337082, 2015). "We used a combination of super-enhancer profiling, near-whole genome shRNA-based and small-molecule screening to identify cyclin D1 and CDK4 as Ewing sarcoma-selective dependencies." (PMID 26337082, 2015). "We show that Ewing sarcoma cells have an activated cyclinD1/CDK4 pathway and are sensitive to both chemical inhibition of CDK4 and shRNA suppression of CDK4 and cyclin D1." (PMID 26337082, 2015).
Ewing sarcoma (continued). "Another mechanism reported to enhance cyclin D1/CDK4 pathway activation in Ewing sarcoma is via the EWS/FLI1 fusion protein binding the CCND1 gene promoter resulting in increased expression of cyclin D1 protein." (PMID 26337082, 2015). "Interestingly, pre-conditioning of CAR-T cells with a CDK4/6 inhibitor increased the anti-tumour effect of oncolytic viruses in a mouse model of Ewing sarcoma." (PMID 40983796, 2025). "Moreover, IGF-IR activation is a mechanism underpinning the resistance to CDK4/6 inhibitor in Ewing sarcoma." (PMID 32493414, 2020). "Additionally, pharmacologic inhibition of CDK4 with selective CDK4/6 inhibitors led to cytostasis and cell death of Ewing sarcoma cell lines in vitro and growth delay in an in vivo Ewing sarcoma xenograft model." (PMID 26337082, 2015). "Toward this end, we integrated the results of super-enhancer profiling, a near-whole genome shRNA screen, and a publically available chemical screening database to identify a dependency of Ewing sarcoma cells on the G1 cell cycle signaling proteins cyclin D1 and CDK4." (PMID 26337082, 2015). "Because CDK4/6 inhibitors primarily induce a G1 cell cycle arrest in cancer cells with a functional Rb protein, we examined the effect of CDK4/6 inhibition on cell cycle in Ewing sarcoma cells." (PMID 26337082, 2015). "In addition, we showed that Ewing sarcoma cell lines are sensitive to the pharmacological inhibition of CDK4/6, both in vitro and in vivo." (PMID 26337082, 2015). "There are also reports of CDK4 gene amplification in Ewing sarcoma." (PMID 26337082, 2015). "To determine whether CCND1 and CDK4 are more highly expressed in Ewing sarcoma versus other tumors, we compared Ewing cells to other tumor types by using the data generated from the Cancer Cell Line Encyclopedia (CCLE)." (PMID 26337082, 2015). "Notably, cyclin D1, as well as its cell cycle regulatory partner, CDK4, were present in all Ewing sarcoma cell lines tested." (PMID 26337082, 2015). "More recently, experiments conducted in Ewing sarcoma cells have demonstrated that IGF1R upregulation promotes resistance to CDK4/6 inhibitors suggesting that dual targeting of CDK4/6 and IGF1R may represent a synergistic combination with potential clinical implications for therapy in this disease." (PMID 33673232, 2021). "There are several proposed mechanisms by which cyclin D1/CDK4 may be deregulated in Ewing sarcoma." (PMID 26337082, 2015). "In fact, they found that the CDK4/6 inhibitor LEE011 (Novartis) has promising in vitro and in vivo cytostatic and cytotoxic activity on Ewing sarcoma cells." (PMID 26802024, 2016). "The aim of the present study was to determine efficacy of cyclin-dependent kinase 4/6 (CDK4/6) and insulin-like growth factor-1 receptor (IGF-1R) inhibitors on the Ewing's sarcoma PDOX." (PMID 27286459, 2016). "We also determined that the cyclin D1 gene (CCND1) is regulated by a super-enhancer and confirmed Ewing sarcoma is selectively dependent on CCND1 and CDK4 compared to other cancer cell lines." (PMID 26337082, 2015). "To complement these shRNA studies, we tested the effects of a selective small-molecule inhibitor of CDK4/6, LEE011, in Ewing sarcoma cells." (PMID 26337082, 2015). "Amplification of the CDK4 and MDM2 genes was found in Ewing's sarcoma." (PMID 37089080, 2023). "Combined treatment with CDK4/6 and IGF-IR inhibitors synergistically inhibits Ewing sarcoma." (PMID 32493414, 2020). "In the context of bone tumors, a recent study suggested that the dual inhibition of CDK4/6 and of IGF-1R may be a candidate synergistic combination for the clinical application in Ewing sarcoma, since CDK4/6 drug resistance is mediated by the activation of IGF-1R signaling." (PMID 32326412, 2020). "Our previous study showed that cyclin-dependent kinase 4/6 (CDK4/6) and insulin-like growth factor-1 receptor (IGF-1R) inhibitors were effective on the Ewing’s sarcoma PDOX, but not doxorubicin, similar to the patient’s resistance to doxorubicin." (PMID 29262551, 2017).